GSK3B (glycogen synthase kinase 3 beta)
Diseases named in the same sentence as GSK3B in open-access papers (continued):
Sharing a sentence is not in itself a finding about the gene and the disease.
diabetes (continued). "Our work expands upon this body of literature, showing that GSK3β inhibition may attenuate diabetes-induced autophagy impairment in HAECs by increasing autophagosome formation, potentially by Akt/AMPK-FOXO1 signalling." (PMID 27534430, 2016). "Atorvastatin normalized activity of Akt and GSK3β, suggesting cellular protection, processes which may contribute to the overall renal protective actions of statin treatment in diabetes." (PMID 27649495, 2016). "Increased GSK-3β activity was found in diabetes and in insulin resistance." (PMID 27851811, 2016). "In summary, this study demonstrated that, in the early stage of STZ-induced diabetes, rats displayed increased myocardial oxidative stress and reduced antioxidant capacity together with impaired Akt/GSK-3β and STAT3 activation, which rendered the diabetic heart more sensitive to IRI." (PMID 24041262, 2013). "Therefore, the inhibition of IPC myocardial protection in the diabetes is most likely related to the activation of GSK-3β." (PMID 21822424, 2012). "Emerging evidence indicates that both IPC- and Ipost-mediated myocardial protection predominantly be mediated by stimulating PI3K/Akt and associated GSK-3β pathway while diabetes-mediated pathogenic effects are found to be mediated by inhibiting PI3K/Akt and associated GSK-3β pathway." (PMID 21822424, 2012). "Two elegant studies from the same group reported recently that GSK-3B overexpression in mice induces β-cell mass restriction and the development of diabetes and that the genetic disruption of GSK-3B in β-cells results in increased β-cell mass in those transgenic mice." (PMID 20942928, 2010). "Elevated level of GSK-3B has been observed to contribute to diabetes development." (PMID 19997558, 2009). "However, the progression into frank diabetes promotes low-grade inflammation, oxidative stress, elevated glucocorticoids, and the pathological activation of GSK3β despite elevated GSK3β-pSer9 that contribute to hyperphosphorylation of tau to impair cognitive functions." (PMID 38416718, 2024). "Thus, diabetes-induced REDD1 expression promotes signaling through GSK3β." (PMID 37392853, 2023). "Glycogen kinase-3β (GSK-3β) may be a link between diabetes and Alzheimer’s." (PMID 38002034, 2023). "It is noteworthy that the enhanced S255 phosphorylation was associated with elevated GSK3β activation, as indicated by decreased phosphorylation of the kinase, and that both MG53 and GSK3β protein levels were significantly upregulated in mice with advanced diabetes." (PMID 36337049, 2022). "Therefore, diabetes-associated targets (AKT1 and PPARγ) and two targets involved in regulating glucolipid metabolism (GSK3β and ADORA1), which have the lowest free energy binding with their compounds, were selected for molecular docking and refined by exploring the specific binding sites." (PMID 36278175, 2022). "In summary, we have demonstrated that the phosphorylation of MG53 at S255 by GSK3β is necessary for its function as an E3 ligase, and that the phosphorylation is markedly enhanced in the heart as well as skeletal muscle of animals with metabolic disorders, in particular, diabetes." (PMID 36337049, 2022). "Additionally, GSK3-β is causally linked with the amyloidogenesis, the abnormal tau hyperphosphorylation at multiple sites and with inflammatory activation, representing thus an important hub between diabetes mellitus (DM) and AD which is also regarded as Type 3 diabetes (T3D)." (PMID 34830036, 2021). "Therefore, the inhibition of GSK-3β might provide an important and alternative therapeutic strategy for the treatment of diabetes." (PMID 33809065, 2021). "Therefore, Met-mediated reductions in diabetes-induced apoptosis might be attributable to activation of the PK2-mediated AKT/GSK3β pathway." (PMID 32508669, 2020).
diabetes (continued). "Moreover, polysaccharide isolated from okra (OP) may enhance the Nrf2 level in the nucleus via the inhibition of GSK-3β signal pathway in the type 2 diabetes mellitus (T2DM) mice, and this effect correlates with decreased liver fibrosis." (PMID 33052244, 2020). "Similarly, using a network-based pharmacological analysis, mulberry extracts have been proposed to regulate TNF-α, PPARγ, glycogen synthase kinase-3 beta (GSK3B), insulin receptor substrate 1 (IRS1), interleukin 6 (IL-6) and other proteins involved in diabetes and obesity associated complications." (PMID 30577684, 2018). "Moreover, AGL in HepG2 cells probably by binding with adenosine A2α receptor activates Nrf-2 transcription and inhibited its exclusion from the nucleus by inactivating GSK-3β, together resulting in activation of HO-1, suggesting an application in the treatment of diabetes and other related diseases." (PMID 28878680, 2017). "It is still unknown whether GSK-3β is involved in diabetes-induced dysfunctional angiogenesis." (PMID 29209632, 2017). "Once GSK-3β could be considered as a potential therapeutic target for diabetes and neurological disorders due to its role in insulin pathway substrates and inflammation process, western blot assays were performed to verify the presence of some age related changes in AKT and GSK-3β activity." (PMID 26647069, 2015). "Although many studies have shown glycogen synthase kinase-3β(GSK-3β) was associated with type 2 diabetes mellitus(T2DM) and implicated with a wide range of cancers, the role of GSK-3β in hepatocellular carcinoma(HCC) and the correlation among GSK-3β, T2DM and HCC remains unclear." (PMID 25157753, 2014). "However, in diabetes, phosphorylation of Akt is reduced and the activity of GSK-3β is increased, which may lead the heart damage to ischemic insult." (PMID 24041262, 2013). "In addition to diabetes, and neurodegenerative disorders, we believe that GSK-3β inhibition may play a promising role in patients receiving irradiation." (PMID 22675363, 2012). "Glycogen Synthase Kinase 3β (GSK3β) is a key protein kinase in the IRSP and plays a significant role in the pathogenesis of Type 2 Diabetes Mellitus (T2DM)." (PMID 40692617, 2025). "This is particularly compelling considering recent evidence suggesting that GSK‐3β could represent a potential link between diabetes mellitus (DM) and AD (sometimes referred to as type 3 diabetes)." (PMID 40530618, 2025). "Our study's main goal was to find out how the compound myricetin interacts with the important regulatory proteins, IR, GSK3β, and GCK, that are involved in diabetes." (PMID 38465169, 2024). "The current study aimed to investigate the potential contribution of liraglutide and pramlintide in the prevention of diabetes-induced cognitive dysfunction and their effect on the PI3K/AKT/GSK-3β/TTBK1 pathway in type 2 diabetic (T2D) rat model." (PMID 38536493, 2024). "Meanwhile, GSK‐3β activity was negatively correlated with MMSE scores (R = −0.49, p < .0001), and positively correlated with diabetes duration, HbA1c, and FPG level." (PMID 37700547, 2023). "The activity of this inhibitor towardother kinases offered the opportunity to study the effect of DYRK1Aand GSK3β kinases on the NFAT pathway, allowing us to predicta positive effect toward β-cell expression and diabetes." (PMID 36883902, 2023). "Irregularity in GSK-3β gives rise to diabetic encephalopathy, diabetic cardiomyopathy, maternal type 1 diabetes, T1DM, and other types of diabetes." (PMID 35359879, 2022). "Calycosin alleviated diabetes mellitus-induced renal inflammation and cognitive impairment by regulating the NF-κB pathway and reducing oxidative stress-mediated PI3K/Akt/GSK-3β signaling, respectively." (PMID 33293989, 2020).
diabetes (continued). "Interestingly, a study reported that diabetes-induced synaptic impairment in the hippocampus of mice can be protected by inhibiting GSK3β, an upstream signaling molecule that upregulates Drp1 activity in diabetic conditions, suggesting that reducing Drp1 activity may have beneficial effects." (PMID 32664237, 2020). "Diabetes significantly decreased the phosphorylation of both AKT and GSK3β in the testis, a change that was reversed by Met." (PMID 31871550, 2019). "Evidence also shows that GSK-3β is a potential link between diabetes mellitus (DM) and AD, and DM might accelerate the progression of AD." (PMID 30426182, 2019). "Diabetes mellitus (DM) in rats was induced by intraperitoneal injection of 1% streptozotocin (STZ), and lithium chloride (LiCl) was used to decrease the expression of GSK-3β." (PMID 30237226, 2019). "In the present study, we studied the expression of Foxo1, Gsk3β and PI3K-Akt-mTOR in the brain of streptozotocin-induced type 2 diabetes mellitus Wistar rats." (PMID 30041644, 2018). "Western blot analysis showed that diabetes dampened phosphorylation of AKT and GSK3β, p-AKT-to-AKT ratio and p-GSK3β-to-GSK3β ratio, and enhanced expression of Bax, Bcl-2, cleaved caspase-3 and TGF-β, which was mitigated in the cathepsin K knockout." (PMID 28821796, 2017). "In the present study, our in vivo and in vitro data showed that diabetes significantly down-regulated AKT/GSK-3β signaling in sham-operated heart while DATS markedly enhanced the phosphorylation levels of AKT and GSK-3β." (PMID 29088824, 2017). "In mice with type 1 diabetes mellitus, treatment with ATOR, at 10 mg-kg−1-d−1, significantly suppressed GSK-3β activation, IKK/IкBα phosphorylation, NF-кB nuclear translocation and caspase-3 activation, while also activating PP2Ac." (PMID 27851811, 2016). "It is clear that IPC produces myocardial protection by phosphorylation of GSK-3β that inhibited the opening of mPTP, but the activity of GSK-3β was found to be elevated during diabetes." (PMID 21822424, 2012). "In rats with STZ-induced diabetes, GSK3β was upregulated, while quercetin supplementation normalized the activity of this enzyme." (PMID 40806520, 2025). "KCLE also improves diabetes by regulating AKT1, TNF, EGFR, and GSK3β." (PMID 40076380, 2025). "Additionally, GSK-3β, the predominant isoform from the GSK-3 family, plays a critical role in both diabetes and neurodegenerative processes." (PMID 39766390, 2024). "When experiencing impaired insulin-related signaling pathways, insulin resistance and hyperinsulinemia, IDE, a degrading enzyme of insulin and Aβ, is considered as a bridge linking diabetes and CI and AD via the potential signaling pathways of PI3K/AKT/GSK3β, PPARγ and NFκB." (PMID 39767690, 2024). "Myricetin interacts with IR, GSK3β, and GCK, which may enhance the effectiveness of diabetes treatments." (PMID 38465169, 2024). "In line with what has been shown in AD animal models, strengthening the gut-brain barrier through probiotic supplementation in a diabetes mouse model down-regulated GSK-3β levels compared to the diseased group without probiotic supplementation." (PMID 37034173, 2023). "Early studies have shown that the GSK-3β inhibitor SB216763 can attenuate myocardial ischemia reperfusion injury in animals without any comorbidities with diabetes mellitus, or hyperlipidaemia." (PMID 37626874, 2023). "The inhibition of GSK3β in vitro and in vivo decreased VCAM1 ectodomain shedding and could possibly offer cardioprotection in diabetes." (PMID 37762417, 2023). "Herein, we explored a role for REDD1-dependent GSK3β activation in promoting canonical NF-κB signaling and consequently the development of diabetes-induced retinal inflammation." (PMID 37392853, 2023). "With the recent findings regarding the crucial roles of GSK3β and DYRK1A in diabetes pathogenesis, we believe that the development of potent and selective inhibitors for these targets could be of great importance to treat both T2D and AD." (PMID 36499613, 2022).
diabetes (continued). "Circulating EVs from people with diabetes carry increased levels of specific phosphorylated kinases (i.e., AKT1, GSK3B, LYN, MAP2K2, MYLK, and PRKCD) and could potentially distribute activated kinases systemically." (PMID 35628588, 2022). "Promising GSK-3β inhibitors are already widely investigated for bipolar disorder, AD, inflammatory diseases, Acquired Immune Deficency Syndrome (AIDS), diabetes and cancer." (PMID 35409221, 2022). "The hepatic protein levels of GLUT4, GSK3β, p-PI3K, and p-AKT are the indices of diabetes." (PMID 35096302, 2021). "Glycogen synthase kinase 3β (GSK-3β) is a widely investigated molecular target for numerous diseases, and inhibition of GSK-3β activity has become an attractive approach for the treatment of diabetes." (PMID 33809065, 2021). "A previous study proved that the activity of GSK-3β in diabetes was as twice as that of non-diabetic patients." (PMID 30237226, 2019). "In addition, in mice with diabetes, the levels of PK2, PKR2, p-Akt, and p-GSK3β were significantly decreased at different times, while that of PKR1 was markedly increased, and these changes were normalized by Met." (PMID 31871550, 2019). "In the present study we have found that after 20 weeks of diabetes, topical administration of GLP-1 resulted in a significant increase not only of these two important neuronal survival factors but of the entire PI3K/Akt/GSK3B/β-catenin pathway." (PMID 30862093, 2019). "Secondly, as type 2 diabetes is the most common form of diabetes, accounting for more than 90% of all cases, it is of great importance to further investigate the potential role of DATS and AMPK-mediated AKT/GSK-3β/HIF-1α signaling pathway under type 2 diabetic condition." (PMID 29088824, 2017). "There was no change in protein expression of AKT or GSK3β for either diabetes or cathepsin K knockout conditions." (PMID 28821796, 2017). "A previous study on myocardial ischemia demonstrated a cardioprotective effect of the B2R agonist in nondiabetic mice and the B1R agonist in diabetes via inhibition of GSK-3β." (PMID 27446506, 2016). "Based on these observations, we hypothesized that diabetes/high glucose increases superoxide anion formation that drives VEGF expression and retinal vascular permeability by activating the GSK3β, β-catenin, uPAR pathway." (PMID 23951261, 2013). "The ten important active constituents were chosen for molecular docking verification with the key targets TNF, AKT1, EGFR, and GSK3β (the core intersection target of the PPI network and Component-pathway-target network), which are considered potential targets in the treatment of diabetes." (PMID 40076380, 2025). "Besides Akt/NF-ĸB and Akt/GSK-3β, other signaling molecules including p38 MAPK, JNK1/2, and Wnt/β-catenin have been reported to be modulated by glabridin and may be involved in diabetes-related osteoporosis." (PMID 40243576, 2025). "The mRNA expression levels of PTEN and GSK-3β were significantly increased, while IRS-1, PI3k, Akt, and GLUT-2 were decreased considerably in the DC group compared to the NC group (p < 0.001), demonstrating the dysregulation of the insulin-mediated PI3K/AKT pathway in diabetes." (PMID 38231654, 2023). "This suggests that inhibition of diabetes-induced retinal molecular modifications and pathological changes in the RPE of Akt2 cKO mice may be due to the upregulation of Akt1 and the downstream inhibition of the GSK3β/NF-κB regulated inflammatory response." (PMID 36229454, 2022). "Decreased GSK3β-Ser9 phosphorylation, increased TNF, IL-6, COX-2, and iNOS expression, and the abolishment of these effects by SB216763 can also be observed in the hippocampi of rats with diabetes induced by a combination of a high-fat diet and low streptozotocin concentrations." (PMID 32231133, 2020).
diabetes (continued). "In summary, our data suggest that PK2 may participate in pathophysiological changes in DCM and that Met protects against diabetes-induced cardiac and remodeling, apoptosis, and dysfunction via activation of the PK2/PKR signaling, thereby regulating the AKT/GSK3β pathway." (PMID 32508669, 2020). "Additionally, inhibiting GSK-3β in silymarin-treated cells did not alter silymarin-induced inhibition of diabetes-induced migration." (PMID 29209632, 2017). "It has been suggested that the diminished potential for cardioprotection in diabetes is due to impaired function of the ATP-dependent potassium channel (KATP-channel), or due to decreased phosphorylation of important signalling kinases including Akt and glycogen synthase kinase (GSK)-3β." (PMID 23051145, 2012). "The activity of GSK-3β is two-fold higher in diabetes than that of nondiabetes." (PMID 21822424, 2012). "We found that in the Akt2fl/fl samples, diabetes increased the level of phospho-Akt2 (but not total Akt2) and increased the ratio of phospho-NF-κB p65/total NF-κB p65, while decreasing phospho-Akt1 and the proportion of phospho-GSK3β/total GSK3β as compared to Akt2fl/fl nondiabetic controls." (PMID 36229454, 2022). "Polymorphisms in glycogen synthase kinase beta (GSK3B), a regulator of glycogen synthase activity, and skeletal muscle glycogen synthase 1 (GYS1) have been examined in several studies, but have generally failed to associate with diabetes or measures of insulin resistance." (PMID 16700901, 2006). "In addition, the content of GSK3β protein in the diabetes control group significantly decreased compared to the healthy control group (P<0.001), while the difference in the content of this protein in the diabetes training group compared to diabetes control group was not significant (P>0.05)." (PMID 37274326, 2023). "We present here a non-exhaustive list of studies using GSK3β and DYRK1A inhibitors as therapeutic approaches for diabetes and AD." (PMID 36499613, 2022). "Total GSK-3β was not altered throughout the observation period, whereas p-GSK-3β increased gradually with duration of diabetes." (PMID 19834568, 2009). "Rats were divided into 4 groups: group 1, normal controls without diabetes; group 2, diabetic controls without treatment; group 3, diabetic rats receiving ESWT; and group 4, rats receiving 6-bromoindirubin-3′oxime (BIO), a GSK-3β inhibitor, to trigger Wnt/β-catenin signaling." (PMID 33396580, 2020).